RNU6-63P (RNA, U6 small nuclear 63, pseudogene)
Synonyms: RNU6-63
Gene: Small nuclear RNA gene on chromosome 13 (27,488,138 to 27,488,232, forward strand). Ensembl gene ENSG00000252499.
Homologues: Orthologues: chimpanzee U6 (100% identical), dog U6 (80% identical). Paralogues in human: RNU6-685P (93% identical), RNU6-144P (88% identical), RNU6-140P (87% identical), RNU6-536P (87% identical), RNU6-80P (87% identical), RNU6-820P (87% identical), RNU6-961P (87% identical), RNU6-1038P (86% identical), RNU6-1119P (86% identical), RNU6-1158P (86% identical), RNU6-20P (86% identical), RNU6-211P (86% identical), and 1290 more.